RN7SL297P (RNA, 7SL, cytoplasmic 297, pseudogene)
Gene: Miscellaneous RNA gene on chromosome 2 (111,930,175 to 111,930,467, forward strand). Ensembl gene ENSG00000240183.
Homologues: Orthologues: chimpanzee Metazoa_SRP (99% identical), macaque Metazoa_SRP (80% identical). Paralogues in human: RN7SL126P (72% identical), RN7SL3 (72% identical), RN7SL503P (72% identical), RN7SL1 (71% identical), RN7SL2 (71% identical), RN7SL597P (71% identical), RN7SL566P (70% identical), RN7SL658P (70% identical), RN7SL679P (70% identical), RN7SL288P (70% identical), RN7SL786P (70% identical), RN7SL709P (69% identical), and 703 more.